RAB27A (RAB27A, member RAS oncogene family)
Diseases named in the same sentence as RAB27A in open-access papers (continued):
Sharing a sentence is not in itself a finding about the gene and the disease.
colorectal cancer (15 papers, 2015 to 2025). A primary or metastatic malignant neoplasm that affects the colon or rectum. "Rab27A is downregulated in colorectal cancer, and reduced expression of Rab27A in colorectal cancer is associated with poor patient survival rates, advanced TNM stage, distant metastasis, and local recurrence." (PMID 30081925, 2018). "Elevated RAB27A has been identified as a positive prognostic marker of colorectal cancer, whereas a decrease of both RAB27A and RAB27B expression correlates with increased metastasis and poor outcome." (PMID 35091681, 2022). "Recently, some studies have found that Rab27a has a close relationship with many human cancers, Rab27a overexpression prefigures unfavourable prognosis in colorectal cancer." (PMID 29212243, 2017). "However, deletion of either Rab27a or nSMase2 significantly inhibits tumor growth in mice, including that of breast, prostate, and colorectal cancers." (PMID 33178688, 2020). "However, the association between Rab27A expression and clinicopathological characteristics of colorectal cancer (CRC) has not been elucidated yet." (PMID 26070933, 2015). "Rab27a knockout suppressed colorectal cancer growth and extended survival in MC38 mice, which is a colorectal cancer model exhibiting a partial response to anti-PD-L1 therapy." (PMID 33178688, 2020).
lung carcinoma (14 papers, 2012 to 2024). "This study reveals that except Rab7a, five Rab proteins, Rab8a, Rab11b, Rab27a, Rab35, and Rab37, were highly expressed in the purified AP of lung cancer cells (CL1‐5‐Q89L) with a high secretory tendency (Q) (column 4 vs. column 3)." (PMID 38804615, 2024). "Either knockdown of Rab27a in lung cancer or gold nanoparticles conjugated with anti-sense Rab27a oligonucleotides to mute Rab27a in BC generate significant inhibition of SEV release." (PMID 37108371, 2023). "Since Rab27a contributes to EV secretion, and is a target of miR-124a, we elected to investigate the role of miR-124a on Rab27a mediated EV release in lung cancer." (PMID 32974168, 2020). "This time, differently from what we measured with Rab27a silencing, Rab32 knockdown was crucial for the observed miR-124a effect on EV release in lung cancer cell lines." (PMID 32974168, 2020). "We then sought to comprehensively examine the respective roles of miR-124a, Rab27a, and Rab32 on EV release in lung cancer." (PMID 32974168, 2020). "We evaluated the effect of miR-124a overexpression in PC9 and H1299 lung cancer cell lines on Rab27a expression." (PMID 32974168, 2020). "We decreased Rab27a expression by both siRNA and miR-124a overexpression in H1299 lung cancer cell lines." (PMID 32974168, 2020). "At the cellular level, four human lung cancer cell lines were selected and screened by Western blot, and the high expression Rab27a cell lines were selected for subsequent silencing experiments." (PMID 29212243, 2017). "By studying the expression of apoptosis protein after Rab27a silencing, the intrinsic mechanism of Rab27a induced growth of lung cancer cells was derived." (PMID 29212243, 2017). "In a word, reduction of Rab27a expression significantly promotes the apoptosis of lung cancer cells, resulting in inhibition of tumor growth." (PMID 29212243, 2017). "A first interesting observation about these genes is that many of them have been positively implicated in breast and/or lung cancer progression and resistance to therapy: AURKA, CAV2, RAB27A, RAD51, TIMELESS, TIMM17A." (PMID 22347440, 2012). "In our research, we first reported that miR-124-3p inhibits the exosome secretion and migratory abilities of NSCLC cells through targeting Rab27a and another function of miR-124-3p-mediated lung cancer progression indicated that PI3K/AKT signaling pathway was regulated by miR-124-3p." (PMID 36600320, 2023). "Interestingly, Linc01703 does not directly impact the proliferation and invasion capabilities of lung cancer cells but rather inhibits cancer metastasis by promoting the secretion of CD81+ exosomes through the Rab27a/SYTL1/CD81 transport complexes." (PMID 38136327, 2023). "We also found higher Rab27a protein levels in the Ca of lung cancer patients." (PMID 36531060, 2022). "In particular, it has been reported that Rab27A regulates EV release in lung cancer cell lines." (PMID 32974168, 2020). "It showed that the target Rab27a gene could increase drug sensitivity of lung cancer cells." (PMID 29212243, 2017). "In lung cancer cells, IFN‐γ triggered annexin A2 (ANXA2) exocytosis via a Rab11‐Rab8a and Rab27a mediated secretory autophagy pathway including the fusion of AP and MVB to form amphisome followed by migration to the plasmid membrane and exocytosis." (PMID 38804615, 2024). "To assess the biological role of Rab32 on EV release and its relationship with miR-124a in lung cancer, we silenced Rab32 and overexpressed miR-124a in a NSLC adenocarcinoma cell line similarly as we did with Rab27a." (PMID 32974168, 2020). "In this study, by RNA interference technology, we investigated the effects of Rab27a gene silencing on the biological characteristics of NSCLC and its role as a potential target for lung cancer treatment." (PMID 29212243, 2017). "In addition, we show that serum lactate levels are positively correlated with serum EV levels and Rab27a and HIF-1α protein levels in the tumor tissues of lung cancer patients." (PMID 36531060, 2022).
lung carcinoma (continued). "However, the mRNA expression levels of Rab27a did not seem to affect the survival of lung cancer patients." (PMID 36531060, 2022).
colon cancer (11 papers, 2016 to 2025). "Several studies have associated increased expression of Rab27a with carcinogenesis, and it has been reported to promote the stemness of colon cancer cells, leading to poor survival in pancreatic cancer." (PMID 34444857, 2021). "Therefore this study was undertaken to delineate the role of Rab27A in colon cancer, especially its influences on cCSCs and its underlying mechanism, as well as its relevance with NF-κB related inflammatory signal pathway." (PMID 27556511, 2016). "Increased expression of Rab27a in colon cancer cells in response to the NF-kB related inflammatory signaling pathway was shown to promote tumorigenesis." (PMID 38715944, 2024). "In this study, we find that the proliferation, migration and invasion of colon cancer cells are significantly suppressed by RAB27A knockdown, but promoted by RAB27A ectopic expression." (PMID 36371494, 2022). "And we found that cell proliferation, clone formation, migration and invasion were suppressed by RAB27A knockdown in SW480 colon cancer cells, but promoted by RAB27A ectopic expression in RKO colon cancer cells." (PMID 36371494, 2022). "It has been reported that RAB27A acts in the downstream of NF-κB signaling pathway to promote the stemness of colon cancer cells via up-regulation of cytokine secretion." (PMID 36371494, 2022). "We found that the proliferation, migration and invasion of colon cancer cells were significantly suppressed by RAB27A knockdown, but promoted by RAB27A ectopic expression." (PMID 36371494, 2022). "A decrease in EV production by MC38 colon cancer cells upon Rab27a knockout led to the release of systemic immunosuppression." (PMID 34623756, 2021). "We demonstrate that hypoxia plays a key role in exosomes secretion from G‐MDSCs through promoting Rab27a expression and respiratory hyperoxia reduces colon cancer cells stemness through inhibiting GM‐Exo production." (PMID 31559140, 2019). "HT29 cell lines with an overexpression of Rab27A (L.V.-Rab27A) were set up to investigate the role of Rab27A in colon cancer stem cells." (PMID 27556511, 2016). "Altogether, our findings reveal a unique mechanism that tumor environment related NF-κB signaling promotes various colon cancer stem cells (cCSCs) properties via an amplified paracrine mechanism regulated by higher Rab27A level." (PMID 27556511, 2016). "Also, migration and invasion of colon cancer cells were shown to be suppressed by RAB27A knockdown but were promoted by RAB27A ectopic expression." (PMID 40229280, 2025). "Collectively, our data demonstrate that RAB27A plays a critical role in colon cancer cell growth." (PMID 36371494, 2022). "In addition, our data demonstrated that the migration and invasion of colon cancer cells were suppressed by RAB27A knockdown, but promoted by RAB27A ectopic expression." (PMID 36371494, 2022). "Therefore, RAB27A is of vital importance for colon cancer development, and may be a valuable prognostic indicator and potential therapeutic target for CRC." (PMID 36371494, 2022). "MDSCs subjected to Rab27a knockdown and SW480 human colon cancer cells were co‐transferred to BALB/c nude mice." (PMID 31559140, 2019). "In two colon cancer cell lines, we observed upregulation of other exocytic RABs including RAB3B, RAB26, and RAB27A as a result of RAB3C overexpression." (PMID 28784136, 2017). "Furthermore, we found that RAB27A ectopic expression promoted RKO cell migration, confirming the vital role of RAB27A in colon cancer cell migration." (PMID 36371494, 2022).
colon cancer (continued). "The migrated cell number in RAB27A knockdown SW480 cells was significantly lower than that in the negative control group, indicating that RAB27A plays a critical role in mediating the migration of SW480 colon cancer cells." (PMID 36371494, 2022). "In addition, we also found that RAB27A knockdown inhibited SW480 cell invasion, whereas RAB27A overexpression facilitated RKO cell invasion, suggesting that RAB27A is of vital importance for colon cancer cell invasion." (PMID 36371494, 2022).
glioma (11 papers, 2012 to 2025). A benign or malignant brain and spinal cord tumor that arises from glial cells (astrocytes, oligodendrocytes, ependymal cells). "Knockdown of Ras-associated protein 27a (Rab27a), a small GTPase, in glioma cells decreased release of small EVs in vitro and slowed tumor growth in vivo." (PMID 34298912, 2021). "In this study, we evaluated the function of Ras-associated protein 27a (Rab27a) in glioma and evaluated the feasibility of assessing its role in EV release in glioma cells in vitro and in vivo." (PMID 33282910, 2020). "The exact mechanisms underlying Rab27a expression and cell viability in glioma and cancer in general remain to be further understood." (PMID 33282910, 2020). "For glioma, Rab27A acted as an oncogenic factor and significantly associated with tumor progression and poor prognosis in all grades of gliomas." (PMID 26070933, 2015). "Rab27a was significantly associated with grade progression and high mortality in all grades of glioma in the discovery set." (PMID 24587032, 2014). "As Rab27a expression was associated with high-grade gliomas and worse prognosis, we screened its expression in different molecular subtypes of WHO Grade IV gliomas." (PMID 24587032, 2014). "In summary, Rab27a expression was significantly associated with grade progression and poor prognosis in all glioma grades, including mesenchymal and G3 subtype and wild-type IDH1, suggesting Rab27a as a novel biomarker with potentially important therapeutic implications." (PMID 24587032, 2014). "The same study also suggested that Rab27a has a vital role in glioma cells’ release of small extracellular vesicles." (PMID 40319095, 2025). "More studies are needed to address the role of Rab27a in glioma in different cell lines and in vivo models." (PMID 33282910, 2020). "As dysregulation of cytokine release plays an important part in glioma pathogenesis, we investigated downstream effects of Rab27a knockdown by evaluating the cytokine release in the media after 72 h." (PMID 33282910, 2020). "The exact relation between Rab27a expression, EV release, cell viability, and cytokine release needs to be further elucidated before Rab27a can be used to study EVs in glioma biology or used with therapeutic intent." (PMID 33282910, 2020). "In glioma, there is an increasing body of research noting the importance of Rab27a in viability and aggressiveness of these tumors." (PMID 33282910, 2020). "To further assess the impact of Rab27a knockdown on GL261 glioma cells, we investigated the growth dynamics of the two cell lines, stably transduced with lentivirus packaged with an expression cassette for firefly luciferase (Fluc), in vivo." (PMID 33282910, 2020). "siRNA mediated knockdown of Rab27a in C6 and U251 glioma cell lines has also resulted in a decrease in cell proliferation and invasion." (PMID 33282910, 2020). "In this study, we confirmed the role of Rab27a in the release of small EVs in glioma in vitro and showed that knockdown of Rab27a resulted in reduced cell viability and increased expression of CCL2." (PMID 33282910, 2020). "Recently, short hairpin mediated knockdown of Rab27a in 73C glioma cells showed decreased growth in vitro and in vivo in a mouse model." (PMID 33282910, 2020). "Rab27A enhanced various ability of glioma cell, such as developing proliferation, promoting invasion and inhibiting apoptosis." (PMID 26070933, 2015). "The data of differential expression of Rab27A in CRC in this present study was consistent with the content of previous reports which stated that expression of Rab27A was significant higher in glioma and HCC." (PMID 26070933, 2015). "High expression of Rab27A showed poor survival in gliomas and HCC as well as suggested favorable survival in GC and CRC simultaneously." (PMID 26070933, 2015). "The expression pattern of Rab27a was validated by immunohistochemistry in another 162 glioma samples from the Chinese Glioma Tissue Database (CGTD)." (PMID 24587032, 2014).
glioma (continued). "By screening the differently expressed genes in the discovery dataset, we found that Rab27a expression was significantly differently between normal brain and all grades of gliomas." (PMID 24587032, 2014). "Both WHO Grade III glioma and WHO Grade IV glioma patients with high or low expression of Rab27a had considerably different prognoses in CGGA." (PMID 24587032, 2014). "To validate the protein expression of Rab27a, we assayed another 162 glioma samples by immunohistochemistry." (PMID 24587032, 2014). "Rab27a expression was significantly associated with grade progression and worse prognosis in all grades of gliomas, suggesting Rab27a as a novel biomarker with potentially important therapeutic implications." (PMID 24587032, 2014). "In the present study, we found that Rab27a was highly expressed in gliomas compared to normal brain tissues in an mRNA microarray dataset from the CGGA." (PMID 24587032, 2014). "Rab27a was more highly expressed in gliomas than in normal brain tissues, and its expression increased with glioma grade progression." (PMID 24587032, 2014). "Rab27a expression was elevated and increased with grade progression of glioma in both the CGGA and the other 2 validation datasets." (PMID 24587032, 2014). "Gene ontology (GO) analysis and gene set variation analysis (GSVA) were used for the functional annotation of Rab27a in 89 WHO Grade IV gliomas." (PMID 24587032, 2014). "Similar to the findings above, Rab27a expression was higher in gliomas than in normal brain tissues, and the protein expression level of Rab27a increased with grade progression in gliomas, which was consistent with our findings above." (PMID 24587032, 2014). "Only two reports have studied the role of Rab27a in promoting proliferation and invasion and suppressing apoptosis in gliomas." (PMID 24587032, 2014). "We down-regulated the expression of Rab27a protein and explored its roles in the invasion and migration in glioma cells." (PMID 23029308, 2012). "RNAi-Rab27A inhibited lysosome cathepsin D exocytosis and glioma cell invasion in an in vitro assay." (PMID 23029308, 2012). "To resolve this conflict, and avoid possible side-effects, we used RNAi to downregulate Rab27a, a key protein in lysosome exocytosis, and determine its effect on glioma invasion." (PMID 23029308, 2012). "Functionally, we demonstrated that RNAi-Rab27A inhibited exocytosis of the lysosome enzyme cathepsin D and inhibition of cathepsin D enzyme activity inhibited glioma cell migration." (PMID 23029308, 2012). "To avoid the possible non-selective effects of GPN and vacuolin-1 on the inhibition of lysosome exocytosis, we assessed the involvement of Rab27A in lysosome-related glioma cell invasion." (PMID 23029308, 2012). "Both Rab27a shRNA and Rab27a siRNA inhibited migration and invasion of C6 glioma cells in transwell experiments with or without ECM gel." (PMID 23029308, 2012). "This highlights the fact that different glioma cell lines might respond differently to knockdown of Rab27a, with some cell lines more affected than others." (PMID 33282910, 2020). "For our study, we focused on the effects of Rab27a in the syngeneic GL261 mouse glioma model." (PMID 33282910, 2020). "In this study, we sought to assess the role of Rab27a in EV release in glioma." (PMID 33282910, 2020). "Furthermore, it encourages further research into the functions of Rab27a in glioma and the role of other, larger, EVs in tumor-to-microenvironment communication." (PMID 33282910, 2020). "However, these two studies only used functional assays in GBM cell lines, and the comprehensive effect of Rab27a on the occurrence and development of glioma and its expression patterns in glioma tissues was still unclear." (PMID 24587032, 2014).
glioma (continued). "Since cathepsin D is a normal and major component of lysosomes, frequently used as a marker, these results confirm that the mechanism by which RNAi-Rab27a inhibits glioma invasion is by inhibiting lysosomal exocytosis of cathepsin D or the extracellular release of other lysosomal enzymes." (PMID 23029308, 2012). "We found that rab27A was expressed in glioma cells, and colocalized with cathepsin D in lysosome." (PMID 23029308, 2012). "The data further confirmed that RNAi-Rab27A inhibit glioma cell migrtion in the in vitro assay." (PMID 23029308, 2012). "In the present study, we found that Rab27a colocolized with cathepsin D in glioma cell lysosomes." (PMID 23029308, 2012). "RT-PCR and Western blot showed that Rab27a normally exists in C6 glioma cells." (PMID 23029308, 2012). "Interestingly, RAB38, a new member of the RAB small G protein family that regulates intracellular vesicle trafficking, RAB27a, as well as RAB34 have all been reported to confer a poor prognosis, associated with malignant progression and subtype preference in gliomas." (PMID 36430705, 2022). "Therefore, Rab27a was a prognostic marker in every grade of glioma." (PMID 24587032, 2014). "However, the prognostic and molecular features of gliomas with Rab27a expression are still unclear." (PMID 24587032, 2014). "Furthermore, Rab27A and cathepsin D colocaolized in glioma cell lysosomes." (PMID 23029308, 2012). "We found that knockdown of Rab27a led to a marked increase in expression of CCL2, a cytokine vital in mediating macrophage, micoglia, and regulatory T cell infiltration in glioma." (PMID 33282910, 2020). "However, as the function of Rab27a in glioma is multifaceted, knocking down Rab27a may have unwarranted downstream effects aside from inhibition of EV release, such as changes in CCL2 expression, and should therefore be used with caution in glioma." (PMID 34298912, 2021). "We assessed the expression status of Rab27a in an independent group of 162 glioma patients by IHC (5 normal tissues, 37 WHO Grade II gliomas, 24 WHO Grade III gliomas, and 96 GBMs)." (PMID 24587032, 2014). "However, given the previously discussed impact of Rab27a knockdown on CCL2 expression, this model may not be able to pin-point the exact mechanisms to study glioma–macrophage interactions via EVs." (PMID 33282910, 2020).